GPC6 (glypican 6)
Description:
Cell surface proteoglycan that bears heparan sulfate. Putative cell surface coreceptor for growth factors, extracellular matrix proteins, proteases and anti-proteases (By similarity). Enhances migration and invasion of cancer cells through WNT5A signaling.
Synonyms: OMIMD1
Tractability: Antibody: its Gene Ontology location is reachable by antibodies, with high confidence; UniProt places it where antibodies can reach, with medium confidence; UniProt predicts a signal peptide or a membrane-spanning region. PROTAC: its protein half-life has been measured.
Gene: Protein-coding gene on chromosome 13 (93,226,807 to 94,408,020, forward strand). Ensembl gene ENSG00000183098.
Subcellular location: Cell membrane; Secreted, extracellular space (Secreted glypican-6)
Subcellular location (Human Protein Atlas): Golgi apparatus; Vesicles
Pathways (Reactome):
Disease: Attachment and Entry; Defective B3GALT6 causes EDSP2 and SEMDJL1; Defective B3GAT3 causes JDSSDHD; Defective B4GALT7 causes EDS, progeroid type; Defective EXT1 causes exostoses 1, TRPS2 and CHDS; Defective EXT2 causes exostoses 2; Dengue Virus Attachment and Entry; Dengue Virus-Host Interactions; RSV-host interactions; Respiratory syncytial virus (RSV) attachment and entry
Metabolism: Glycosaminoglycan-protein linkage region biosynthesis; HS-GAG biosynthesis; HS-GAG degradation
Hemostasis: Initiation of coagulation cascade; Regulation of clotting cascade
Sensory Perception: Retinoid metabolism and transport
Gene Ontology:
Molecular function: protein binding; coreceptor activity
Biological process: cell migration; regulation of neurotransmitter receptor localization to postsynaptic specialization membrane; regulation of signal transduction
Cellular component: nucleus; cell surface; extracellular matrix; Golgi lumen; lysosomal lumen; plasma membrane; synapse; extracellular region
Genetic constraint (gnomAD): Loss-of-function variants: 13 observed, 53.78 expected, observed/expected ratio (o/e) 0.24, 90% interval 0.16 to 0.38. The upper end of that interval is the gene's LOEUF score, 0.38, which puts it in group 1 of 6, group 1 being the genes least tolerant of losing a copy. Missense variants: 635 observed, 733.84 expected, observed/expected ratio (o/e) 0.87, 90% interval 0.81 to 0.92. Synonymous variants: 278 observed, 272.51 expected, observed/expected ratio (o/e) 1.02, 90% interval 0.92 to 1.13.
Homologues: Orthologues: chimpanzee GPC6 (100% identical), macaque GPC6 (99% identical), dog GPC6 (99% identical), pig GPC6 (98% identical), guinea pig GPC6 (98% identical), rabbit GPC6 (97% identical), mouse Gpc6 (97% identical), rat Gpc6 (89% identical), tropical clawed frog gpc6 (81% identical), zebrafish gpc6a (67% identical), zebrafish gpc6b (57% identical), Drosophila melanogaster dlp (37% identical). Paralogues in human: GPC4 (63% identical), GPC1 (45% identical), GPC2 (42% identical), GPC5 (26% identical), GPC3 (25% identical).
Diseases named in the same sentence as GPC6 in open-access papers:
GPC6 is named in the same sentence as 65 diseases in open-access papers, as found by Europe PMC text mining. Sharing a sentence is not in itself a finding about the gene and the disease. The quoted sentences say what the papers report.
breast carcinoma (10 papers, 2013 to 2025). "Glypican (GPC)-6 (GPC6) was reported to modulate invasive migration in breast cancer cells and was transcriptionally regulated by NFATc2." (PMID 39436410, 2025). "We looked for experimentally supported interactions with GPC1, GPC3, GPC4, and GPC6 as these are the glypicans we found to have the highest impact on the prognosis of breast cancer patients." (PMID 33742285, 2021). "To approach this research question, firstly we utilized a large cohort of breast cancer patients to analyze the impact GPC1 to GPC6 have on their relapse-free survival." (PMID 33742285, 2021). "Constitutive activation of NFAT1 drives breast cancer cell migration and invasion in vitro, apparently via the induction of glypican-6 (GPC-6), cyclooxygenase-2 (COX-2), autotoxin, and prostaglandins." (PMID 32397368, 2020). "GPC6 is related to various tumors including prostate cancer, non-small cell lung cancer, colorectal cancer, gastric cancer, early stage ovarian cancer, nasopharyngeal carcinoma, and breast cancer." (PMID 35265226, 2022). "In the future, GPC1, GPC3, GPC4 and GPC6 might possibly serve as a basis for the medical treatment of breast cancer patients." (PMID 33742285, 2021). "Expression of GPC6 has been observed in drug-resistant breast cancer cell lines." (PMID 24804215, 2014). "In this study, our aim was to identify whether any member of the glypican family, glypican-1 to glypican-6, has a prognostic impact on the survival of breast cancer patients and could potentially act as therapeutic targets in the battle against the most common cancer in women." (PMID 33742285, 2021). "In the four-gene prognostic signature, EXOC6, GPC6, and NFATC2 were correlated with aggression of breast cancer." (PMID 35265226, 2022). "In summary, we have found promising results in our study suggesting the prognostic power of GPC1, GPC3, GPC6 and potentially also GPC4 expression on the survival of breast cancer patients." (PMID 33742285, 2021). "It has been found that NFAT1 promotes breast cancer cell motility and invasion by regulating COX-2 and glypican-6." (PMID 26461225, 2015). "The basal breast cancer cell lines MDA-MB-453 and MDA-MB-468 show a similar glypican gene expression pattern, with high expression of GPC1 and GPC4 and MDA-MB-231 shows a high expression of GPC1 and GPC6." (PMID 33742285, 2021). "Furthermore, GPC6 promotes invasive migration of breast cancer cells through a noncanonical Wnt5A signaling pathway." (PMID 26448945, 2015). "A study has shown that GPC6 promotes the invasive migratory capacity of breast cancer cells through non-canonical Wnt5a signaling, where NFAT signaling promotes GPC6 expression in the cells." (PMID 33742285, 2021).
autosomal recessive omodysplasia (7 papers, 2010 to 2023). Autosomal recessive form of omodysplasia. "Homozygous or compound heterozygous mutations in GPC6 are associated with autosomal recessive omodysplasia." (PMID 37396033, 2023). "In mice, Gpc6 is critical to modulating the response of the growth plate to thyroid hormones; while in human, mutations in the region where Gpc6 resides on Chromosome 13 are associated with defects in endochondral ossification and cause recessive omodysplasia." (PMID 28610618, 2017). "Loss of function mutations in GPC6 lead to impaired endochondral ossification and cause the short stature condition omodysplasia." (PMID 24148222, 2013). "Other upregulated genes included GPC6 (loss of function mutations result in the short stature condition omodysplasia) as well as zinc finger protein of cerebellum 1 (ZIC1) and PCP4 both of which are known to be differentially expressed in tumours." (PMID 24148222, 2013). "Also, autosomal recessive omodysplasia is a genetic condition characterized by severe short stature and congenital heart defects, caused by homozygosity for null mutations in GPC6." (PMID 20360844, 2010). "However, the ability of glypican-4 to uncouple pluripotent stem cell differentiation from tumorigenic potential has been recorded, while the reduced expression or loss of function of glypican-6 has been described in retinoblastoma and autosomal-recessive omodysplasia." (PMID 29940912, 2018). "GPC6 has a broad expression pattern which includes the developing brain, and defects in human GPC6 result in omodysplasia (severe limb shortening and facial dysmorphism)." (PMID 24098140, 2013).
schizophrenia (7 papers, 2011 to 2025). A major psychotic disorder characterized by abnormalities in the perception or expression of reality. "GPC6 has recently been identified as a gene that confers susceptibility to formal thought disorder in schizophrenia and as a factor released from astrocytes that supports the formation of glutamatergic synapses via GluA1 AMPA receptors." (PMID 23447498, 2013). "Finally, some members of the HSPG protein family, like GPC4, GPC5 and GPC6 have been linked to neurodevelopmental diseases such as autism, schizophrenia." (PMID 29434536, 2018). "Interesting to note were the differentially expressed genes in mix-TH-VGLUT3 neurons in schizophrenia (in total 10), including increased expression of glypican 6 (GPC6) in schizophrenia compared to controls." (PMID 39397771, 2025).
ovarian carcinoma (6 papers, 2015 to 2022). A malignant neoplasm originating from the surface ovarian epithelium. "The context and cancer-specific characteristics of the different glypicans yet again become obvious when we look at the fact that in ovarian cancer, high GPC6 expression correlated with increased overall survival." (PMID 33742285, 2021). "It has previously been shown that miR-509-3p mimics also suppressed expression of GPC6 and other transcripts (e.g., SNAI2 and TWIST) associated with EMT in ovarian cancer cell lines." (PMID 31199813, 2019). "According to our results, early stage ovarian cancer patients with low mRNA levels of GPC6 and TMEM132D exhibit significantly reduced overall survival compared to patients with high levels of GPC6 and/or TMEM132D." (PMID 26448945, 2015). "In the present study, we validated by qPCR the expression of two genes encoding the transmembrane proteins GPC6 and TMEM132D in a cohort of early stage ovarian cancer patients." (PMID 26448945, 2015). "Ultimately, we performed a retrospective survival analysis of the early stage ovarian cancer patients and correlated the mRNA levels of GPC6 and TMEM132D with the overall survival." (PMID 26448945, 2015). "More importantly, we showed that early stage ovarian cancer patients with high mRNA levels of at least one of the two genes, GPC6 and TMEM132D, exhibited increased overall survival compared to patients with low levels of both genes." (PMID 26448945, 2015). "In this study, we documented an association between the expression of GPC6 and TMEM132D with CD8+ T-lymphocyte infiltration and favorable prognosis in early stage ovarian cancer." (PMID 26448945, 2015). "Further studies are required in order to shed light on the role of GPC6 in ovarian cancer and the mechanism of CD8+ T-lymphocyte infiltration." (PMID 26448945, 2015). "Indeed, individual glypicans have been identified as prognostic factors in oesophageal squamous cell carcinoma (GPC1), hepatocellular carcinoma (GPC3) and ovarian cancer (GPC6)." (PMID 33742285, 2021). "For example, monitoring tumoral GPC6 and TMEM132D mRNA levels could facilitate the identification of early stage ovarian cancer patients at high risk." (PMID 26448945, 2015). "Taken together, our data indicate GPC6 and TMEM132D as potential markers for CD8+ T-lymphocyte infiltration, favorable prognosis, and survival benefit in early stage ovarian cancer." (PMID 26448945, 2015). "In order to validate the expression of GPC6 and TMEM132D in early stage ovarian cancer, we measured by qPCR their mRNA levels in tumor samples from 38 stage I-II ovarian cancer patients (resp)." (PMID 26448945, 2015). "We validated with qPCR the expression of GPC6 and TMEM132D in a cohort of stage I-II ovarian cancer patients." (PMID 26448945, 2015). "Importantly, Kaplan-Meier survival analysis revealed that high mRNA levels of GPC6 and/or TMEM132D correlated significantly with increased overall survival of early stage ovarian cancer patients (p = 0.032)." (PMID 26448945, 2015). "GPC6 and TMEM132D expression was also documented in a variety of ovarian cancer cell lines." (PMID 26448945, 2015). "In the present study, we evaluated the expression of two other overexpressed genes, GPC6 and TMEM132D, and investigated whether they could represent novel prognostic markers of survival in early stage ovarian cancer." (PMID 26448945, 2015). "Thus, the mRNA expression levels of GPC6 and TMEM132D correlate with CD8+ T-lymphocyte infiltration in early stage ovarian cancer." (PMID 26448945, 2015). "In conclusion, GPC6 and TMEM132D could serve as potent markers of CD8+ T-cell infiltration in early stage ovarian cancer." (PMID 26448945, 2015). "To investigate whether GPC6 and TMEM132D expression correlates with CD8+ T-lymphocyte infiltration in early stage ovarian cancer, we used qPCR to quantify the mRNA levels of the CD8A marker in the same cohort of patients." (PMID 26448945, 2015).
ovarian carcinoma (continued). "Thus, GPC6 and TMEM132D may serve as predictors of CD8+ T-lymphocyte infiltration and as favorable prognostic markers in early stage ovarian cancer with important consequences for diagnosis, prognosis, and tumor immunobattling." (PMID 26448945, 2015). "Therefore, we suggest that GPC6 and TMEM132D mRNA levels could serve as markers of CD8+ T-cell infiltration and survival prognosis in early stage ovarian cancer." (PMID 26448945, 2015). "Moreover, we quantified by qPCR the relative expression of GPC6 and TMEM132D in a variety of ovarian cancer cell lines and demonstrated that the expression of both genes is not restricted to the infiltrating immune cells and may actually originate from the tumor cells." (PMID 26448945, 2015).
heart failure (5 papers, 2016 to 2025). Inability of the heart to pump blood at an adequate rate to meet tissue metabolic requirements. "Glypican-6 is required for skeletal and intestinal development and is implicated in heart failure, which results in its upregulation." (PMID 38750698, 2024). "Importantly, GPC6 expression correlated negatively with EF, suggesting, like in mice, that increased GPC6 levels were associated with more progressed heart failure." (PMID 27768722, 2016). "To investigate whether increased BMP4 levels were associated with increased GPC6 expression after AB in mice and human heart failure, we measured BMP4 mRNA in the LV." (PMID 27768722, 2016). "Furthermore, the finding that GPC6 levels in biopsies from patients with end-stage heart failure correlated with reduced EF suggested that GPC6 levels are associated with severity of heart failure." (PMID 27768722, 2016). "This study investigates regulation of the glypican proteoglycan family in experimental and clinical heart failure and demonstrates that GPC6 affects cardiomyocyte signaling and growth." (PMID 27768722, 2016). "To identify direct regulators of cardiac GPC6 expression, we treated cultured fibroblasts with inflammatory mediators, growth and neurohumoral factors central to heart failure." (PMID 27768722, 2016). "In conclusion, our data suggests that glypican-6 plays a role in clinical and experimental heart failure progression by regulating cardiomyocyte growth through ERK signaling." (PMID 27768722, 2016). "Altogether, the upregulation of GPC6 mRNA and protein during hypertrophic remodeling and dilatation in response to LV pressure overload suggests a role for GPC6 in heart failure progression." (PMID 27768722, 2016). "Previously, adenoviral overexpression of glypican-6 in cultured cardiomyocytes was shown to increase protein synthesis and induce hypertrophy and heart failure signature genes, suggesting glypican-6 as a relevant ADAMTS1 and ADAMTS5 target in cardiac development." (PMID 38750698, 2024). "In summary, we show that glypican-6 is upregulated in experimental and clinical heart failure." (PMID 27768722, 2016). "Thus, in cardiomyocytes, increased GPC6 levels induced the expression of heart failure signature molecules and growth through ERK1/2 activation." (PMID 27768722, 2016). "Interestingly, NCM overexpressing GPC6 showed increased mRNA levels of heart failure signature molecules ANP and BNP (respectively)." (PMID 27768722, 2016). "Here we investigated glypicans (GPC1-6), a family of evolutionary conserved heparan sulfate proteoglycans anchored to the extracellular leaflet of the cell membrane, in experimental and clinical heart failure, and explored the function of glypican-6 in cardiac cells in vitro." (PMID 27768722, 2016). "Importantly, adenoviral overexpression of glypican-6 in cultured cardiomyocytes increased protein synthesis and induced mRNA levels of the pro-hypertrophic signature gene ACTA1 and the hypertrophy and heart failure signature genes encoding natriuretic peptides, NPPA and NPPB." (PMID 27768722, 2016). "MR analysis identified significant causal associations between the genes implicated in BW loss (ADD3, HSPA12A, SLC18A2, PDZD8, DUSP5, CASP7) as well as EF% and LV volumes (GPC6, UGGT2, SLAIN1, POU4F1, MBNL2) in BXD mice post-DOX and heart failure (HF) outcomes in humans." (PMID 40321772, 2025).